ZNF662 (zinc finger protein 662)
Description:
May be involved in transcriptional regulation.
Synonyms: FLJ45880
Tractability: No criterion of Open Targets' tractability assessment is met for any kind of drug.
Gene: Protein-coding gene on chromosome 3 (42,905,941 to 42,919,334, forward strand). Ensembl gene ENSG00000182983.
Subcellular location: Nucleus
Subcellular location (Human Protein Atlas): Cytosol; Nuclear bodies
Pathways (Reactome):
Gene expression (Transcription): Generic Transcription Pathway
Gene Ontology:
Molecular function: protein binding; DNA-binding transcription factor activity; RNA polymerase II cis-regulatory region sequence-specific DNA binding
Biological process: regulation of transcription by RNA polymerase II; regulation of DNA-templated transcription
Cellular component: nucleus
Genetic constraint (gnomAD): Loss-of-function variants: 7 observed, 8.8 expected, observed/expected ratio (o/e) 0.8, 90% interval 0.45 to 1.48. That is too few expected variants to judge how well the gene tolerates losing a copy. Missense variants: 540 observed, 533.47 expected, observed/expected ratio (o/e) 1.01, 90% interval 0.94 to 1.09. Synonymous variants: 180 observed, 184.01 expected, observed/expected ratio (o/e) 0.98, 90% interval 0.87 to 1.11.
Homologues: Orthologues: macaque ZNF662 (96% identical), chimpanzee ZNF662 (91% identical), dog ZNF662 (88% identical), pig ZNF662 (71% identical), Drosophila melanogaster CG11902 (25% identical), zebrafish znf574 (23% identical), Drosophila melanogaster CG10631 (22% identical), Drosophila melanogaster CG11696 (18% identical). Paralogues in human: ZNF671 (36% identical), ZNF667 (36% identical), ZNF865 (24% identical), ZNF710 (21% identical), ZNF366 (19% identical), ZNF783 (15% identical), ZNF212 (14% identical).
Diseases named in the same sentence as ZNF662 in open-access papers:
ZNF662 is named in the same sentence as 9 diseases in open-access papers, as found by Europe PMC text mining. Sharing a sentence is not in itself a finding about the gene and the disease. The quoted sentences say what the papers report.
Oral Squamous Cell Carcinoma (2 papers, 2025 to 2026). "In addition, ZNF662 has been reported as a valuable biomarker in oral squamous cell carcinoma 24-26." (PMID 40612670, 2025).
breast carcinoma (1 paper, 2025). "We further demonstrated that the promoter hyper-methylation of ZNF662 was the main cause of its down-regulation in breast cancer." (PMID 40612670, 2025). "We found that down-regulation of ZNF662 in breast cancer was associated with abnormal promoter methylation." (PMID 40612670, 2025). "Online database analysis revealed that higher expression of ZNF662 is associated with better prognosis of breast cancer patients." (PMID 40612670, 2025). "Next, we assessed the prognostic significance of ZNF662 expression and methylation level in patients with breast cancer." (PMID 40612670, 2025). "The survival analysis indicated breast cancer patients with high expression of ZNF662 had a better survival probability, while hyper-methylation of ZNF662 promoter might contribute to a worse prognosis." (PMID 40612670, 2025). "We found that ZNF662 was lowly expressed in breast cancer tissues and cells." (PMID 40612670, 2025). "Furthermore, we found significantly higher methylation levels at multiple sites of ZNF662 in breast cancer tissues using MethylTarget® analysis." (PMID 40612670, 2025). "In summary, these results indicated that ZNF662 was down-regulated through promoter hyper-methylation in breast cancer, suggesting that ZNF662 might function as a tumor suppressor gene." (PMID 40612670, 2025). "To further determine whether ZNF662 silencing was a result of promoter methylation, we treated breast cancer cells with DNA methyltransferase inhibitor Aza and histone deacetylase inhibitor TSA." (PMID 40612670, 2025). "Additionally, we detected the expression of ZNF662 in breast cancer cell lines." (PMID 40612670, 2025). "It was illustrated that ZNF662 was lowly expressed in breast cancer tissues compared to normal breast tissues." (PMID 40612670, 2025). "We found that the expression of ZNF662 was almost absent in most breast cancer cell lines." (PMID 40612670, 2025).
head and neck squamous cell carcinoma (1 paper, 2026). A squamous cell carcinoma that arises from any of the following anatomic sites: lip and oral cavity, nasal cavity, paranasal sinuses, pharynx, larynx, and salivary glands. "ZNF662 was consistently downregulated in tumors, and higher ZNF662 expression was associated with improved survival in an independent head and neck squamous cell carcinoma cohort." (PMID 42123571, 2026).
triple-negative breast carcinoma (1 paper, 2025). An invasive breast carcinoma which is negative for expression of estrogen receptor (ER), progesterone receptor (PR), and human epidermal growth factor receptor 2 (HER2). "ZNF662 over-expression inhibited triple-negative breast cancer cell proliferation, migration and invasion and induced cell cycle arrest in vitro, and also suppressed the growth and metastasis of xenograft tumors in vivo." (PMID 40612670, 2025).
cancer (1 paper, 2025). A tumor composed of atypical neoplastic, often pleomorphic cells that invade other tissues. "Thus, we aimed to investigate whether the ZNF662-NGF axis could modulate the sensitivity of TNBC cells to anti-cancer drugs, particularly EGFR inhibitors." (PMID 40612670, 2025).
tumor (1 paper, 2025). "In this study, we confirmed the tumor-suppressive effect of ZNF662 in TNBC and revealed the underlying mechanism." (PMID 40612670, 2025). "Therefore, we investigated whether the NGF-STAT3/NGF-PI3K signaling axis could be associated with the tumor suppressor phenotypic change caused by ZNF662." (PMID 40612670, 2025). "The tumor growth curve and tumor weight in nude mice receiving subcutaneous injection of ZNF662-overexpressing MB231 cells were significantly reduced." (PMID 40612670, 2025). "Having confirmed the tumor suppressor function of ZNF662 in vitro, we proceeded to investigate its function in vivo by employing nude mouse xenograft models." (PMID 40612670, 2025). "Online analysis demonstrated promoter methylation status of ZNF662 was positively correlated with tumor progression." (PMID 40612670, 2025). "Immunohistochemistry illustrated that Ki67, which is generally regarded as a marker of cell proliferation, was significantly decreased in ZNF662-overexpressing xenograft tumor tissues." (PMID 40612670, 2025). "Collectively, our results showed that ZNF662 functioned as a tumor suppressor in TNBC through suppressing NGF signaling axis." (PMID 40612670, 2025). "In summary, our results indicated that ZNF662 may act as a tumor suppressor gene in TNBC by reducing the expression of NGF." (PMID 40612670, 2025). "Results suggested that over-expression of NGF could reverse the tumor-suppressive effect of ZNF662 in TNBC cells." (PMID 40612670, 2025). "Thus, we considered whether we could combine lapatinib with other chemotherapeutic agents to manage TNBC after detecting the expression or methylation status of ZNF662 in tumor samples." (PMID 40612670, 2025). "In conclusion, ZNF662 might be a new tumor suppressor in TNBC." (PMID 40612670, 2025). "In the present study, we identified a novel tumor suppressor gene of the KRAB-ZFPs family in TNBC, ZNF662." (PMID 40612670, 2025). "However, how ZNF662 influences tumor progression remains unclear." (PMID 40612670, 2025).
ZNF662 also shares sentences with these, for which no sentence is quoted: breast tumor (1 paper); endometrial cancer (1); metastatic tumors (1).